CHEK2 (checkpoint kinase 2)
Diseases named in the same sentence as CHEK2 in open-access papers (continued):
Sharing a sentence is not in itself a finding about the gene and the disease.
cancer (continued). "Not all carriers of CHEK2 mutations develop cancer, even though they are somewhat frequent (0.3–1.6% in the general population, up to 5.7% in individuals with a family history)." (PMID 40507526, 2025). "However, knowledge of deactivating variants in tumour suppressors can also have important implications for diagnostics; for instance, both CHEK2 and STK11 variants are difficult to assess in the context of hereditary cancers." (PMID 41152984, 2025). "Pan-cancer analysis of the TCGA database also suggests that the rate of CHEK2 mutations, and not simply the level of CHEK2 expression, are associated with higher frequencies of somatic mutations." (PMID 40492861, 2025). "The potential interaction between JAK2-mediated signaling pathways and cell cycle control functions modulated by CHEK2 could shed light on shared mechanisms or synergies in the pathogenesis of certain hematologic disorders and malignant neoplasms." (PMID 40177144, 2025). "While clonal haematopoiesis for CHEK2 variants has previously been reported in several cancer types, we detected no systematic differences in variant allele frequency (VAF) in our data between cases and controls (p = 0.803)." (PMID 40034715, 2025). "Ten patients had germline mutations affecting cancer predisposition genes not typically linked to WT: CHEK2 in 4 children, and BLM, BRCA2, CDKN2A, FMN2, PIK3C3, and STK11 in one patient each." (PMID 40340749, 2025). "Other homologous recombination DNA damage repair (HR-DDR) genes associated with other cancer risks besides breast and ovarian, such as ATM (n = 9), BARD1 (n = 4), BRIP1 (n = 2), CHEK2 (n = 5), PALB2 (n = 5), RAD51C (n = 1), and RAD51D (n = 7), accounted for an additional 4% (33/769)." (PMID 40065011, 2025). "Among three sons of the index patient, two did not have a cancer diagnosis, one of whom was CHEK2 wild‐type while the other carried the variant." (PMID 40072281, 2025). "Our study suggests that the risk of DCIS in a woman with a CHEK2 mutation is not determined solely by the presence of the mutation; penetrance is also dependent on her family history of cancer." (PMID 40770660, 2025). "Given that CHEK2 GPV carrier status was not a significant predictor of these cancer risk management practices indicates that uptake of these treatments does not significantly differ between the 1100delC and I157T groups." (PMID 39062660, 2024). "Pathogenic variants of ATM (ataxia-telangiectasia mutated), CHEK2 (checkpoint kinase 2), PALB2 (partner and localizer of BRCA2), and XRCC2 (X-ray repair cross-complementing 2) tumor suppressor genes (TSGs) have been associated with the development of cancers." (PMID 38784039, 2024). "The CHEK2 status did not associate with a particular OC histology; most (4/6) CHEK2 GPV carriers had a positive family cancer history." (PMID 39003285, 2024). "In summary, our data show that CHEK2-deficient cancers are not driven by disruption of HRR as genomic instability features and a mutational signature indicative of HRD are lacking." (PMID 38848470, 2024). "Indeed, 94.5% of the 1,519 CHEK2 missense variants reported on ClinVar10 are classified as variants of uncertain significance (VUS), limiting genetic diagnosis of CHK2-dependent cancers." (PMID 39642869, 2024). "Compared to heterozygotes, carriers of homozygous or compound heterozygous CHEK2 GPV have substantially higher cancer risk, develop tumors at younger age, but otherwise do not develop other clinical symptoms." (PMID 38554551, 2024). "We cannot state with certainty that the P/LP BRCA2, CHEK2, HOXB13, and MITF variants contributed to the patient's cancer, these might also be secondary findings." (PMID 38415346, 2024).
cancer (continued). "The authors’ approach coupled with negative clinical trials using PARPi in CHEK2-mutated cancers highlights the importance of identifying functional HRD before the use of a specific gPV as a biomarker for PARPi use." (PMID 38950525, 2024). "PVs in BRCA1, BRCA2, CHEK2, and ATM have been linked to a wide variety of cancers." (PMID 38929805, 2024). "Although CHEK2 PVs were observed in a wide range of cancer types, there are no reliable additional cancer risks associated with CHEK2 PVs, besides BC." (PMID 38339330, 2024). "Next to the observed tissue-specific mutational signatures, breast and non-breast CHEK2-deficient cancers present with comparable mutational signature profiles (available online)." (PMID 38848470, 2024). "Another important derivative, W-2b, induced premature senescence associated with galactosidase activity, G2/M cell cycle arrest, and increased phosphorylation of the checkpoint kinase-2 (Chk2) in cancer cells, indicating that the W-2b derivative can inhibit tumor growth in a carcinoma model." (PMID 37259311, 2023). "Similarly, CHEK2 protein expression was upregulated in all cancer types on the basis of the data from the UALCAN database." (PMID 38081888, 2023). "However, using CHEK2 as a predictive marker remains challenging due to its limited penetrance in cancer patients and its high prevalence among control subjects." (PMID 38136334, 2023). "Drug screening was performed with a custom panel of 42 small molecule drugs selected based on standard-of-care chemotherapies, drugs targeting common cancer genes and pathways for LGSOC, and the genomic profile of the patient’s tumor, which included a CHEK2 mutation and several VUSs." (PMID 37202426, 2023). "Biallelic alteration of CHEK2 was not identified within this cohort, although biallelic germline or somatic alterations are uncommonly found in adults with CHEK2-associated cancers." (PMID 36980535, 2023). "Inhibition of CHEK2 by AZD7762 was also reported to increase bone remodeling, indicating that better CHEK1/2 inhibitors may be used to treat cancer and prevent bone loss during bone metastasis." (PMID 37862420, 2023). "Additionally, the CHEK2 microdeletion was unveiled in a young patient with a strong family history of cancer." (PMID 37628581, 2023). "In this study, we examined CHEK2 expression levels in various cancers." (PMID 38081888, 2023). "Targeting CHEK2 with selective inhibitors could be a potential strategy to protect ovaries during cancer treatments and mitigate ovarian aging in cancer survivors." (PMID 37862420, 2023). "Due to historic ascertainment bias in the population under study for cancer predisposition, as well as limitations in tumor genomic profiling assay content and design, the frequency and clinical meaning of CHEK2 variation have not been fully defined." (PMID 36980535, 2023).
cancer (continued). "Likewise, a recent investigation suggested that CHEK2 governs energy production in cancer cells by affecting both glycolysis and mitochondrial functions." (PMID 38081888, 2023). "In addition, prior studies have reported epigenetic silencing (e.g., CHEK2 promoter methylation) as a mechanism of downregulating CHEK2 expression in other cancer types." (PMID 35406559, 2022). "Molecular aberrations that were shared in at least one P/X pair and that were previously recognized to have deleterious effects in human cancers included CHEK2 [K416E; 415S (SNP)], EGFR (158N), ATM (P1054R), STK11 (D194N), PIK3CA (E545K), KIT (798I; M541L), and RUNX1 (L56S)." (PMID 34714554, 2022). "A large cross-sectional study evaluated the frequency of different cancer types in germline carriers of (likely) pathogenic CHEK2 variants versus non-carriers." (PMID 35101071, 2022). "In addition to the recommendation for genetic counseling, three variants likely associated with an autosomal dominant cancer disposition supported a treatment recommendation, twice for PARP inhibition (BRCA1, CHEK2) and once for CDK4/6 inhibition (CDKN2A)." (PMID 35918329, 2022). "The next step was to verify the presence of additional pathogenic and clinically relevant variants in CHEK2 and PALB2 genes that may be associated with increased cancer risk in the analyzed samples." (PMID 35456488, 2022). "Carriers of variants in moderate penetrant genes, such as the CHEK2 gene, have been shown to experience increased distress, likely due to the lack of clarity on cancer risk and optimal surveillance." (PMID 35128723, 2022). "Other pathogenic CHEK2 variants noted in our database included p.I157T and c.444+1G>A, which have also been seen by others, although cancer risks associated with many of these variants are not known." (PMID 35040284, 2022). "This family has no cancers typically associated with the CHEK2 pathogenic variant, and in this family, the patient’s grandfather, father, and uncle all expired, so the pedigree verification was not conducted." (PMID 35281821, 2022). "Furthermore, upon comparing the groups demonstrating alterations of CHEK2 and JAK2 (mutations and copy number variation, n = 703) with an unaltered group (n = 37045), several cancer-related genes were found to be preferentially altered in the former." (PMID 35851582, 2022). "Finally, survey of the literature identified two case reports and one family with homozygous CHEK2 mutation with multiple cancers, including NSCLC,3, 4, 5 and two germline surveys of CHEK2 mutations in NSCLC." (PMID 36061833, 2022). "Taken together, these data suggest that genome alterations due to lowered or loss of CHEK2 and JAK2 expression may exacerbate cancer progression and predict poor patient survival." (PMID 35851582, 2022). "Although our detected CHEK2 somatic mutations were not inherited or passed on, their heterozygosity was similar and induced cancer risk." (PMID 35846154, 2022). "While prevalences for ATM, BRCA1, BRCA2, and PALB2 in this study are consistent with prevalences observed in the literature, we calculated that as many as 1.22% of individuals in both cohorts unselected for personal or family history of cancer harbored GPV in CHEK2." (PMID 35805029, 2022). "However, at present, no CHEK1 inhibitors have been approved in Phase 3 clinical trials, due in part to cumulative normal tissue toxicities, off-target effects of simultaneous CHEK2 inhibition, and inefficient drug delivery in cancer patients." (PMID 34090465, 2021). "The identification of BRIP1 and CHEK2 variants in FC HBC or HBOC syndrome families, which have also been reported in BC and OC cases from other populations, supports their role in the risk of these cancers." (PMID 34298626, 2021).
cancer (continued). "CHEK2 LOH was found in the cancer tissue of II-1, and IHC staining showed Chk2 expressed in adjacent normal cells but not in cancer cells, indicating second-hit somatic inactivation of the WT allele in cancer cells." (PMID 34549727, 2021). "Germline variants in the HR pathway, comprising at least 10 genes, such as BRCA1, BRCA2, ATM, BARD1, BRIP1, CHEK2, NBS1(NBN), PALB2, RAD51C, and RAD51D, lead to inherited susceptibility to specific types of cancers, including those of the breast, ovaries, prostate, and pancreas." (PMID 35008774, 2021). "The patient from the BZ16 family who carried the CHEK2 likely pathogenic mutation was diagnosed with GC at the age of 25 years and did not have a family history of cancer." (PMID 34567566, 2021). "A similar enrichment for signature 3 was found for PALB2 and RAD51C mutations or epigenetic silencing of the BRCA1 or RAD51C promoter, but not for inactivation of other cancer-associated genes, such as CHEK2 and ATM." (PMID 33670893, 2021). "In addition, as many as 4% of these individuals have germline pathogenic mutations in cancer predisposition genes other than BRCA1 and BRCA2 on MGPT (i.e. CHEK2, PALB2, ATM, NBN, PTEN, etc.)." (PMID 33541411, 2021). "This is consistent with the CHEK2 LOH in cancer tissue detected by WES." (PMID 34549727, 2021). "Similarly, biallelic CHEK2 PV carriers were significantly more likely to have at least two primary cancers when compared to monoallelic PV carriers (32.3% vs. 13.5%, p = 0.0061)." (PMID 31993860, 2020). "Notably, biallelic CHEK2 PV carriers with at least one primary cancer were significantly younger at the time of diagnosis compared to monoallelic carriers (44 and 47 years, respectively; p = 0.0268)." (PMID 31993860, 2020). "This variant has low penetrance because it does not confer the same level of cancer risk as other CHEK2 pathogenic variants." (PMID 32570972, 2020). "No mechanistic data are available for PrCa, but patients with CHEK2 mutations are among those showing a high response rate to treatment with the poly-ADP ribose polymerase inhibitor Olaparib when cancers were no longer responding to standard treatments." (PMID 32183364, 2020). "Biallelic CHEK2 PV carriers also appeared to have a higher risk of cancer overall, although we did not observe a statistically significant excess of any individual cancer other than breast." (PMID 31993860, 2020). "Similarly, 50.4% of CHEK2 c.1100del monoallelic carriers were unaffected while only 12.5% of CHEK2 c.1100del homozygous carriers were unaffected by any cancer (p = 0.0022)." (PMID 31993860, 2020). "In regard to cancer, in patient 52, we discovered the presence of variants (c.1437_1439delGGA, p.Glu480del, and rs587778541) in the MUTYH gene and (c.470T > C, p.Ile157Thr, and rs1787996) in the CHEK2 gene." (PMID 32695137, 2020). "CHEK2 mutations rank among the most frequent germline alterations revealed by germline genetic testing for various hereditary cancer predispositions, but their interpretation is not trivial." (PMID 33322746, 2020). "Similarly, homozygous carriers of CHEK2 c.1100del with at least two cancers were significantly younger than monoallelic carriers in this category (47 and 36 years, respectively; p = 0.0476)." (PMID 31993860, 2020). "Individuals carrying bi-allelic CHEK2 mutations have a normal phenotype; however, they carry an increased cancer risk in comparison with heterozygotes and noncarriers." (PMID 33322746, 2020).
cancer (continued). "Our first patient was a 63 year old male with no personal history of cancer who presented to our clinic with a family history of a pathogenic CHEK2 mutation." (PMID 30152102, 2018). "The level of cancer risk associated to PALB2 pathogenic variants is known to be low in comparison to BRCA2 pathogenic variants, but enough to propose a clinical management of the familly contrary to other low risk genes, notably CHEK2 1100delC and ATM." (PMID 29707112, 2018). "Additionally, ~6% of women (20/333) were carriers of the pathogenic or likely pathogenic variants in other cancer-related genes, with NBN and CHEK2 reported as the most frequently mutated, accounting for 1.8% (6/333) and 1.2% (4/333) of cases, respectively." (PMID 30441849, 2018). "Interestingly, CHEK2 down-regulation using specific siRNA increased the expression/secretion of both cancer-promoting cytokines SDF-1 and IL-6, and transdifferentiated stromal fibroblasts to myofibroblasts." (PMID 27484185, 2016). "Similarly, BRCA1 and CHEK2 were suggested to participate in cancer development by modulating DNA repair and cell cycle checkpoints in collaboration with FOXM1 and E2F1, respectively." (PMID 26001967, 2015). "Furthermore, somatic mutations of SOD1 are rare in cancer, and those few that do occur are mutually exclusive of those occurring for RAD54B, BLM and CHEK2." (PMID 26318585, 2015). "A missense variant I157T affects the forkhead-associated (FHA) domain, where it mediates ATM-dependent CHEK2 phosphorylation and targeting of CHEK2 to bind partners such as BRCA1 and is associated with reduced DNA repair ability and increased risk for various cancers." (PMID 25431674, 2014). "Clinical testing for CHEK2 has been available for years, yet medical management of patients with CHEK2 mutations is not well-defined; and cancer screening recommendations are primarily based on patients' personal and family medical histories." (PMID 24506336, 2014). "To evaluate the mechanism by which TGF-α protects cancer cells from mitotic catastrophe, we examined the expression and phosphorylation of checkpoint kinase 2 (Chk2), which is known as both a regulator of mitotic catastrophe and as a kinase that phosphorylates survivin in response to DNA damage." (PMID 23588995, 2013). "CHEK2, phosphorylated at T68, is also commonly activated in cancers and precancerous lesions." (PMID 23401782, 2013). "Thus, in these patients with clear familial history of cancer, the evaluation of mutations in other genes, like PALB2, CHEK2 and RAD51C, should also be considered." (PMID 22655046, 2012). "NCBI Entrez gene database reported that: CHEK2 is a cell cycle checkpoint regulator and putative tumor suppressor, and associated with GBM; GSTM5 was reported to be involved in cancer, BCL11A is a proto-oncogene, and FN1 is involved in tumor metastasis and angiogenesis." (PMID 21114830, 2010). "Three of four siblings would not be at elevated risk for the index cancer and we would observe poor segregation in families between cancer and the presence of CHEK2 mutation." (PMID 19401704, 2009). "Ideally, we would compare cancer risks in relatives with and without CHEK2 mutations, but the requirement of collecting a blood or tissue sample from all first-degree relatives, living and dead, was prohibitive." (PMID 19401704, 2009). "Except from the patient harboring the Ile364Thr mutation who did not have any known congestion of cancer disease in the family, a detailed assessment of family cancer history was performed for each patient harboring a germline CHEK2 mutation." (PMID 18725978, 2008).